IGFBP2 (insulin like growth factor binding protein 2)
Diseases named in the same sentence as IGFBP2 in open-access papers (continued):
Sharing a sentence is not in itself a finding about the gene and the disease.
cancer (continued). "In contrast, blocking individual cytokines (IGFBP-3, IGFBP-2, VEGF, PDGF-AA, IL-6 or IL-31) in A549-fibrocyte co-culture CM using neutralizing antibodies decreased ET1 and ETA on cancer cells." (PMID 36241617, 2022). "Dormant cancer cell-derived exosomes reprogrammed the metabolic process of BMSCs through transferring exosomal IGF-2 and IGFBP2." (PMID 36568212, 2022). "As a migration and invasion inhibitory protein and a metastasis suppressor, MIIP was reported to bind to and antagonize the function of diverse effectors, including IGFBP-2, HDAC6 and PAK1, depending on different molecular context in different cancer types." (PMID 31092266, 2019). "It is also notable that we identified over 10 cancer-related genes (including PHGDH, CCND1, IGFBP-2, XAGE1B/E, CYP4F22, RBM11, ORAOV1, MDK, UGT3A5, SSX5, FBL, NKX2) potentially overexpressed in EFT tumors." (PMID 30093970, 2018). "In relation to serum IGFBP‐2, the findings in this study confirm observations in other reports that baseline IGFBP‐2 in patients with cancer is prognostic for poorer outcome in patients with cervical 36, pancreatic 37, and ovarian 11 cancer." (PMID 29722920, 2018). "In conclusion, this study provides the first demonstration of Hsp27 as the upstream regulator of IGFBP2 and indicates that Hsp27 mediates the regulation of HCC cancer metastasis in vitro and in vivo." (PMID 28903396, 2017). "We conclude that the pro-proliferative effect of IMP2 in most cancer derived cell lines is mediated predominantly by upregulation of IGF2 production and suppression of Grb14 and IGFBP2 polypeptide abundance which together facilitate IGF2 signaling." (PMID 28753127, 2017). "Still, most studies focused on autocrine effects of these two secreted proteins in cancer cells, while our data suggest a paracrine effect whereby HSC derived IGF2 and IGFBP2 influence IGF-signaling in HCC cells." (PMID 26020769, 2015). "The 2Chr7:1n,1d cells exhibited a more invasive phenotype by expressing higher levels of the pro-invasive genes (IGFBP2, PDGFRA, RHOC, FOXM1, and PLAU) and matrix metalloproteinase 2 (MMP2), all of which are well-reported for cancers, including GBM." (PMID 24282558, 2013). "To evaluate the pan-cancer robustness of our 4-gene signature (MAOB, IGFBP2, SERPINA1 and LGR6), we leveraged the ICBatlas database—comprising 93,000+ patients across 18 cancer types (including 12 cancers with multi-omics profiling) and 30 immune checkpoint inhibitor (ICI) treatment cohorts." (PMID 40821817, 2025). "(E) SKM contractile activity-induced decreases in IGF-1, IGFBP-2, and insulin levels and increased IGFBP-1 and -3 levels may also help to limit cancer development in SKM." (PMID 38928185, 2024). "Among the potential interacting proteins with IGFBP2 obtained from the BioGRID and String databases, we focused on an integrin α subfamily member, ITGA5, which is known to play a crucial role in various cancers according to recent studies." (PMID 38918360, 2024). "While not the most highly increased protein on the list, IGFBP2 is of particular interest in aging and cancer." (PMID 39007351, 2024). "Additionally, IGFBP2 facilitates IGF signaling, which is crucial for cancer cell proliferation and survival." (PMID 39766076, 2024). "Furthermore, according to the results from CCLE analysis, IGFBP2, IGFBP3, IGFBP4 and IGFBP6 are highly expressed in most cancer cell lines at the cell level." (PMID 37088808, 2023). "In addition, IGFBP2 and IGFBP7 showed different prognostic roles in multiple cancer types, we therefore created forest plots to show specific predictive effects in various types of cancer." (PMID 37088808, 2023). "As IGFBP-2 is the main binding protein and inhibitor of IGF-1 and therefore inhibits its pro-proliferative action, it would be logical for IGFBP-2 to be downregulated in patients with cancer." (PMID 38137390, 2023).
cancer (continued). "These experiments demonstrate that exogenous IGFBP2 does not bind to the surface of cancer cells, suggesting that the anti-invasive effects are occurring through binding of IGFBP2 to something in the cancer microenvironment." (PMID 37436978, 2023). "The prognostic value of IGFBP2 for OS was not altered by subgroup analyses where studies were regrouped according to cancer types, ethnicity, publication year, NOS score, treatments, and populations." (PMID 35546443, 2022). "On the other hand, the role of both IGFBP2 and IGFBP6 in cancer remains less clearly understood." (PMID 35688943, 2022). "Furthermore, stimulating cancer cells with recombinant IGFBP-3, IGFBP-2, VEGF, PDGF-AA or IL-31 led to upregulation of ET1 and ETA." (PMID 36241617, 2022). "Notably, IGFBP-2, IGFBP-3, and IGFBP-5 participate in a wide variety of ncRNA-regulated pathways, with both stimulatory and inhibitory effects on cancer cell functions." (PMID 35597813, 2022). "The exposition of cancer cells to methylation inhibitor (5-Aza-2′-Deoxycytidine (AZA)), produced re-expression of IGFBP2, and increased in abundance of IGFBP2, indicating that IGFBP2 could be epigenetically silenced." (PMID 33498859, 2021). "Furthermore, published cancer surface markers CD44 and CD59, as well as the insulin-like growth factor binding protein 2 (IGFBP2), were expressed in all analyzed CSCs." (PMID 33800955, 2021). "Later on, the enhanced expression of the SASP factors CXCL12, HGF, MMPs and TGFβ in irradiated fibroblasts was reported to increase EMT and invasiveness of cancer cells, and enhanced expression of the SASP factors EGF, FGF-4, GM-CSF, IGF-1,2, IGFBP-2,4,6 induced chemoradioresistance in cancer cells." (PMID 32384619, 2020). "The role of IGFBP2 has been studied in angiogenesis and many types of cancers, but not in chicken skeletal muscle development." (PMID 30999686, 2019). "Mechanistic insights are still required to explain the cytotoxic effects we observed, but the identification of RBM11, CYP4F22 and IGFBP-2 as new potential drug targets for EFT would seem to confirm the utility of this open source, computational methodology for cancer drug discovery." (PMID 30093970, 2018). "Furthermore, the baseline concentrations of IGFBP‐2 and PAPP‐A were virtually similar when comparing patients with cancer and healthy controls." (PMID 29722920, 2018). "As in MEFs, deletion of IMP2 from the cancer cell lines is accompanied by a marked increase in the abundance of Grb14 and IGFBP2, and overexpression of IMP2 reduces the abundance of both the IGFBP2 and Grb14 polypeptides." (PMID 28753127, 2017). "Because our study found that MMP-2 is up-regulated at the mRNA level in MCF-7 cells treated with CAA-CM and MMP-2 is a proteinase which has been verified to promote cancer metastasis, we detected MMP-2 in MCF-7 cells treated with CAA-CM and CM plus with IGFBP-2." (PMID 25747684, 2015). "Our three biomarker panel consists of IGFBP2, DKK3 and PKM2, and each of these proteins are known to be biologically important in CRC disease and progression and are representative of the heterogeneous nature of this cancer." (PMID 25793510, 2015). "In addition, we have also found that ICA-CUR could affect cancer cell development and the level of PD-L1 by targeting the DNMT1/IGFBP2 axis, which in turn influences the differentiation of immune T cells." (PMID 38778379, 2024). "IGFBP2 and IGFBP7 expression may impact the prognosis of more cancer types." (PMID 37088808, 2023). "The pro-tumoural effects of MCP-1, proliferin, TIMP-1 and soluble ICAM-1 whilst the anti-cancer effects of IGFBP-2, endostatin and ADAMTS-1 have been published and suggest that this secretome signature may well provide a combination of effects on cancer growth." (PMID 33730293, 2021).
cancer (continued). "Additionally, cross-talk between MMP-7 and MMP-9 leads to the cleavage of insulin-like growth factor-binding protein 2 (IGFBP-2), an angiogenic activator in major aggressive cancers via the transcriptional regulation of the VEGF gene, showing adverse effects in cancer angiogenesis in some tissues." (PMID 31921634, 2019). "Moreover, EVs can affect receptor cell function, and dormant cancer cell-derived EVs promote PMN formation and cancer cell survival in the bone marrow by reprogramming the metabolic processes of bone marrow mesenchymal cells through the transfer of EVs IGF-2 and IGFBP2." (PMID 38037077, 2023). "However, it is not known how IGFBP2 is regulated in cancer cells, or whether IGFBP2 has oncogenic activity in RCC." (PMID 28931862, 2017). "The results showed that, except for IGFBP1 and IGFBP2, the expression of other IGFBP genes was significantly correlated with MSI in several cancer types, and the vast majority also showed negative correlation." (PMID 37088808, 2023). "The HR values for OS and PFS were 1.57 (95% CI = 1.31–1.88) and 1.18 (95% CI = 1.04–1.34), respectively, which showed that there was a significantly negative correlation between IGFBP2 expression and OS, PFS in cancer patients." (PMID 35546443, 2022). "The CTGF, IGFBP2, JAG1, and SPARC promoters can provide higher transgene expression in fibroblasts than in cancer cells, but the nonspecific viral promoters CMV, SV40, and the recently studied universal PCNA promoter have the same features." (PMID 33804861, 2021). "Interestingly, six genes, including ALS2, DAPL1, HS6ST1, IGFBP2, MGC12982, PPIAL4C, are selected in all predictions, i.e., when no samples is removed, or one cancer type data is removed." (PMID 35349572, 2022).
cardiovascular disease (15 papers, 2021 to 2025). "Based on the DEG between IS etiologies and its association with cardiovascular diseases in previous studies, we selected three over-represented genes in EVs for further validation; namely, IGFBP-2 and PECAM-1 increased in EVs from CE patients, and NECTIN-2 overexpressed in AT patients." (PMID 38673963, 2024). "In light of those findings, it is highly likely, that the association of preoperative IGFBP2 with all-cause mortality is a marker of a higher burden of cardiovascular disease at baseline and that the dynamics during cardiac surgery probably represent further myocardial injury." (PMID 38379859, 2023). "One study in a community setting has shown that, while IGFBP-1 alone predicted incident heart failure and cardiovascular disease mortality, IGFBP-2 and IGF-I were more useful in a multimarker model." (PMID 39595651, 2024). "Several proteins linked to increased risk of cardiovascular disease were upregulated in male iVSMCS (PCK2, CD109, and IGFBP2)." (PMID 39796045, 2024). "To date, however, studies evaluating the influence of IGFBP-2 levels on cardiovascular disease remain scarce." (PMID 36970368, 2023). "In the Framingham population study (n = 3523, mean 62 y, 53% F) over nearly 30 years, higher IGFBP-1, IGFBP-2 and IGF-I predicted cardiovascular disease mortality." (PMID 39595651, 2024).
metabolic disease (13 papers, 2013 to 2026). A congenital disorder (due to inherited enzyme abnormality) or acquired (due to failure of a metabolically important organ) disorder resulting from an abnormal metabolic process. "Of note, abnormal expression of other IGFBP such as IGFBP-1 and IGFBP-2 was detected in different states of metabolic disorders where reduced serum levels of both proteins were associated with cardiovascular risk factors." (PMID 24340035, 2013). "These associations may be important to understand the etiology of IGFBP2 in metabolic disorders associated with diet." (PMID 33498859, 2021). "However, although the mechanisms by which IGFBP2 participates in the development of obesity-related diseases are still controversial, there is more and more evidence for a solid association between serum IGFBP2 and these metabolic disorders." (PMID 33498859, 2021). "The physiological role of IGFBP2 on metabolic disorders are controversial and less defined, although there is growing evidence for a solid association." (PMID 33498859, 2021). "Investigating the molecular pathways of IGFBP2 could help to better understand the role that IGFBP2 plays in metabolic diseases." (PMID 33498859, 2021). "Moreover, the functional roles of IGFBP-2 in metabolic diseases and signaling are still unclear and controversial." (PMID 31547433, 2019). "Although the effect of IGFBP-2 in preventing metabolic disorders is well known, its regulatory mechanism remains unclear." (PMID 25695641, 2015). "Thus, the metabolic role of IGFBP2 could place it as a potential regulator in metabolic disorders, either by IGFs/IGFBP2-dependent and independent model." (PMID 33498859, 2021). "Therefore, understanding metabolic regulation of IGFBP2 and its influence on metabolic diseases could provide new insights that can be applied as therapeutic targets." (PMID 33498859, 2021). "Dysregulation of IGFBP-2 has been found to modulate IGF signaling extracellularly and intracellularly, influencing gene expression and cell signaling, leading to various cardiovascular and metabolic diseases." (PMID 40278353, 2025). "However, the physiological pathways have not been explored yet, and the relevance of IGFBP2 as an important pathway integrator of metabolic disorders is still unknown." (PMID 33498859, 2021).
neurodevelopmental disorder (11 papers, 2012 to 2025). A behavioral and cognitive disorder with onset during the developmental period that involves impaired or aberrant development of intellectual, motor, or social functions. "Although the changes were not significant, we observed minor changes in the growth factors, M-SCF, IGFBP-6, IGFBP-2, IGF-2 and PDGF-AA in ZIKV infected astrocytes, which may contribute to ZIKV associated neurodevelopmental disorders." (PMID 30735502, 2019).
psychiatric disorder (7 papers, 2017 to 2025). A disorder characterized by behavioral and/or psychological abnormalities, often accompanied by physical symptoms. "Interestingly, we found that 10Hz flicker mitigated stress-induced changes in transcription of microglial receptors P2ry12 and stress associated receptors such as Nr3c1 and Tlr4, as well as microglial Igfbp2, a key gene implicated in affective and psychiatric disorders." (PMID 40791511, 2025). "Thus, IGFBP-2 may associate with cellular senescence related to psychiatric disorders." (PMID 31824433, 2019). "On the other hand, IGFBP-2 may have some link with psychiatric disorders." (PMID 31824433, 2019).
adenocarcinoma (6 papers, 2012 to 2026). A common cancer characterized by the presence of malignant glandular cells. "Conversely, IGF2BP1 and IGFBP2 expressions significantly correlated with IGF-1 and IGF-2 expressions and adenocarcinoma incidence (p < 0.05)." (PMID 31480481, 2019).
infection (6 papers, 2015 to 2025). The state of being infected such as from the introduction of a foreign agent such as serum, vaccine, antigenic substance or organism. "The results imply that IGFBP2 is commonly down-regulated at advanced stages of infection, correlating with the effects of prolonged HPV16 E6 and E7 expression and reduced levels of IGFBP2 in CIN1 disease may indicate a propensity to progress to a high grade." (PMID 26107517, 2015). "Infection with either Gram-negative (p = 0.548) or Gram-positive (p = 0.747) bacteria did not notably alter plasma IGFBP-2 levels in comparison to all patients not infected by Gram-positive or Gram-negative bacteria, respectively." (PMID 38137505, 2023).
kidney disease (5 papers, 2012 to 2024). "Larger studies including the assessment of IGFBP2 localization and expression in kidney should provide more definitive evidence for the value of IGFBP2 as a clinical diagnostic marker for various kidney diseases." (PMID 33641616, 2021). "Previous reports have also indicated elevated IGFBP-2 levels in patients with kidney diseases." (PMID 38137505, 2023). "Eighteen differentially expressed proteins were found to overlap between the CKD and post-transplant CKD groups including biomarkers of kidney disease (cystatin C, β2-microglobulin, and REN) and biomarkers of inflammation (CFD, IGFBP-2, PRSS 2, Chemokine Ligand 15 (CCL-15), and TNFRSF-1B)." (PMID 33888746, 2021).
neurodegenerative disease (5 papers, 2021 to 2024). A disorder of the central nervous system characterized by gradual and progressive loss of neural tissue and neurologic function. "We next used quantitative immunoblotting to verify the MS data for a subset of candidate biomarkers, with a focus on proteins known to have a role in neuron biology, neuroinflammation, neurodegenerative diseases, and/or pathophysiology in general: NP1, Ch3L1, CD14, and IGFBP2." (PMID 34054689, 2021).
neurological disorders (3 papers, 2020 to 2024). "Here, the authors show a link between P2Y1 receptor, a major regulator of the aberrant Ca2+ signals, and IGFBP2 that may lead to neuronal hyperexcitability in neurological disorders." (PMID 39117630, 2024). "We analyzed publicly available datasets whether P2ry1/P2RY1 and Igfbp2/IGFBP2 transcripts are upregulated in other neurological disease models." (PMID 39117630, 2024). "Thus, IGFBP2 may be a therapeutic target for neurological diseases in which reactive astrocytes upregulate P2Y1R." (PMID 39117630, 2024). "Nevertheless, the finding of both IGFBP2 and P2Y1R upregulation in the astrocytes of two distinct disease models, and the data indicating that IGFBP2 enhances neuronal excitation, indicate that our identified mechanism is relevant to astrocyte–neuron communication in neurological diseases." (PMID 39117630, 2024).
bacterial infection (2 papers, 2023 to 2024). "The use of endotoxin, bacterial infection, as well as SARS-CoV-2 infection induce systemic inflammation, and this can lead to higher levels of IGFBP-2 in the serum." (PMID 38255230, 2024). "The plasma IGFBP-2 levels in patients without bacterial infection were similar to those with Gram-negative (61 patients), Gram-positive (22 patients), or both types of bacterial infections (20 patients) (p = 0.064)." (PMID 38137505, 2023). "Biomarkers for the early detection of bacterial infections are still lacking, so we analyzed whether IGFBP-2 could differentiate between these groups." (PMID 38255230, 2024).
benign neoplasm (2 papers, 1996 to 2021). A neoplasm which is characterized by the absence of morphologic features associated with malignancy (severe cytologic atypia, tumor cell necrosis, and high mitotic rate). "IGFBP-2 mRNA was detected in all ovarian specimens and was 2- to 30-fold higher in malignant than in benign neoplasms." (PMID 8624265, 1996). "IGFBP-2 was the major binding protein in tissue extracts, as measured by both Western ligand blotting and immunoblotting, and was significantly higher in malignant than in benign neoplasms." (PMID 8624265, 1996).
endocrine disorders (2 papers, 2016 to 2023). "However, subsequent findings indicate that increased IGFBP2 levels are associated with not only endocrine disorders but also development of multiple cancer types." (PMID 36712921, 2023).
bone disorder (1 paper, 2018). "Since IGFBPs can bind to IGFs to inhibit or potentiate their bioactivity, it is conceivable that IGFBP2 dysregulation could affect IGFs signaling in the development and maintenance of skeletal and dental tissues, contributing to tooth/bone disorders." (PMID 29875795, 2018).
connective tissue diseases (1 paper, 2022). "We also detected the levels of plasma IGFBP2 in other connective tissue diseases (e.g., RA and SS)." (PMID 36008635, 2022).